SIRT7 (sirtuin 7)
Diseases named in the same sentence as SIRT7 in open-access papers (continued):
Sharing a sentence is not in itself a finding about the gene and the disease.
tumor (continued). "Firstly, the level of SIRT7 is significantly higher in PCa tumors and expressionist level is correlated with the grade of the tumor." (PMID 29100388, 2017). "Moreover, SIRT7 inactivation in Hep3B cells caused a strong reduction of in vivo tumor growth rate and tumor size, confirming the same molecular alterations observed in vitro, hypothesizing sirtuin-7 targeting or miR-125a/b restoration as possible therapeutic strategies in HCC." (PMID 27918441, 2016). "Strikingly, overexpression of this sirtuin protects tumor cells against genotoxic damage and facilitates cell survival, suggesting the possibility that SIRT7 acts an oncogenic role by enhancing genome integrity in tumor cells." (PMID 27916001, 2016). "In colorectal cancer, SIRT7 expression levels were significantly correlated with tumor stage, lymph node metastasis, and poor outcomes." (PMID 27379175, 2016). "MMTV-PyMT/Wnt5a-/- tumors also exhibited increased SIRT7 expression distributed throughout the tumor compared to those derived from MMTV-PyMT/Wnt5a+/+ mice." (PMID 27500936, 2016). "First,we show that while SIRT7 expression is higher in tumor compared to normal controltissues, SIRT7 levels are even more dramatically elevated in metastatic tissuecompared to primary tumors." (PMID 25923013, 2015). "Incidentally, both adenovirus and SV40 are DNA tumor viruses, which cause H3K18ac depletion, plausibly through mobilization of de-acetylase SIRT7, which perhaps is a general feature of the transformation programs driven by DNA tumor viruses." (PMID 26442981, 2015). "Overexpression of RPS7 in presence of HBx led to a severe reduction in the colony formation ability of cells, clearly highlighting that RPS7 acts as a tumor suppressor to restrict the oncogenic potential of HBx-SIRT7 axis." (PMID 26442981, 2015). "Over the past few years, growing evidence has indicated that SIRT7 has importantroles in regulating oncogenic transformation and tumor biology." (PMID 25923013, 2015). "Survival analysis did not reveal any significant differences in disease-free or disease-specific survival time between patients whose tumours had low or high SIRT7 nuclear expression." (PMID 26121130, 2015). "It has been reported earlier that the recruitment of SIRT7 to the promoters of genes with tumor suppressive activities such as RPS7 couples H3K18 deacetylation to transcriptional repression." (PMID 26442981, 2015). "Studies of SIRT7 expression in human tumor tissues suggest that increased SIRT7 levelsmay correlate with enhanced tumor aggressiveness." (PMID 25923013, 2015). "SIRT7 may be required to maintain the tumourigenic phenotype rather than to initiate cellular transformation as its expression was necessary for anchorage-independent growth, proliferation in low serum conditions, loss of contact inhibition and growth of tumour xenografts." (PMID 26121130, 2015). "The same study also identified SIRT7 as a transcriptional repressor of p21WAF1/Cip1 and a target of tumor suppressor micro-RNAs, attesting to its oncogenic potential in hepatocarcinogenesis." (PMID 26442981, 2015). "Our data regarding patient outcome with high nuclear expression of SIRT 7 being associated with prolonged survival and increased time to relapse, are consistent with a tumour suppressive role for SIRT7." (PMID 26121130, 2015). "NEPC may also rely more heavily on class I HDACs and sirtuins such as SIRT1 and SIRT7, which promote dedifferentiation, transcriptional silencing, and tumor aggressiveness." (PMID 41601922, 2026). "In other solid tumors, SIRT7 is highly enriched at promoters of tumor suppressor genes such as nucleoside diphosphate kinase A (NME1), and COP9 signalosome complex subunit 2 (COPS2), as well as the ribosomal protein genes, to inhibit their transcription and promote cell growth and invasion." (PMID 41601922, 2026).
tumor (continued). "Furthermore, the ability of SIRT7 to both repress and enhance PD-L1 expression, depending on the tumor lineage, underscores its bi-functional nature within this regulatory system." (PMID 41425553, 2025). "In most cases, SIRT7 is well known for its tumour-promoting functions." (PMID 40941028, 2025). "If similar mechanisms operate in tumor cells, SIRT7 could attenuate immune surveillance by restraining pathway activation, thereby limiting anti-tumor responses." (PMID 41471367, 2025). "Thus, the epigenetic silencing of retrotransposons represents another mechanism through which SIRT7 preserves genome integrity and likely helps counteract tumor initiation." (PMID 41471367, 2025). "Thus, it is plausible that SIRT7 exerts its tumor-suppressive functions, at least in part, by safeguarding the integrity of rDNA repeats; however, direct experimental evidence is still lacking." (PMID 41471367, 2025). "Moreover, elevated SIRT7 expression correlates with aggressive tumor phenotypes and poor patient prognosis, positioning it as a promising therapeutic target." (PMID 41471349, 2025). "In parallel, we integrate evidence on how canonical biological processes governed by SIRT7—including metabolism, genome stability, and inflammatory signaling—intersect with immune regulation and may thereby influence tumor progression." (PMID 41471367, 2025). "Generally, SIRT7 is widely considered an oncogene due to its upregulation in many tumor types." (PMID 40165597, 2025). "In most cases, SIRT7 is well known for its tumor-promoting functions." (PMID 40149343, 2025). "In addition, studies have shown that miR-21-5p promotes tumor progression by regulating the ubiquitination of SIRT7; while miR-148b-3p, miR-770 and PYCR1 protein target SIRT7 to inhibit its expression or transcription." (PMID 40241794, 2025). "SIRT7 has emerged as a multifaceted regulator of tumor initiation and progression, capable of functioning as either a tumor suppressor or a pro-tumorigenic factor depending on the cellular context, through its control of diverse molecular pathways extensively characterized in prior studies." (PMID 41471367, 2025). "A previous study indicates that SIRT7 is increased in tumor tissues compared with normal tissues." (PMID 38360598, 2024). "However, once cells acquire a malignant phenotype, SIRT7 appears to exert either tumor-suppressive or pro-oncogenic functions in a context-dependent manner." (PMID 38383727, 2024). "Intriguingly, SIRT7 appears to be a potent tumor suppressor in HNSCC." (PMID 38383727, 2024). "In summary, SIRT7 extensively modifies substrates in tumor cells, which may regulate the VEGF/VEGFR signaling pathway in tumor cells, modulating tumor angiogenesis." (PMID 39519130, 2024). "The anti-tumor effect of SIRT7 is mainly achieved through its remodeling of chromatin." (PMID 39479446, 2024). "Furthermore, SIRT7 inhibition significantly impeded DDX3X-mediated tumor growth both ex vivo and in vivo." (PMID 38316768, 2024). "Notably, the dualistic role of SIRT7 is observed not only across a spectrum of malignancies but also within distinct tumor subtypes and at different phases of tumor progression." (PMID 38383727, 2024). "Additionally, SIRT7 plays and indispensable role in promoting anti-tumor effects of intermittent fasting." (PMID 38383727, 2024). "This evidence illustrates how SIRT7 may exert opposite pro-tumorigenic or tumor-suppressive functions across different malignancies by controlling the same signaling pathway." (PMID 38383727, 2024).
tumor (continued). "SIRT7, found exclusively in eukaryotes, is the least researched sirtuin, and has been linked to various non-neoplastic and tumorous diseases, such as cardiovascular diseases, obesity and NSCLC." (PMID 39020302, 2024). "These compelling findings suggest that SIRT7 could potentially wield substantial tumor-suppressive influence, at least within a subset of hematologic malignancies." (PMID 38383727, 2024). "However, a contrasting pattern emerges in high-grade and invasive BCa cases, where SIRT7 levels exhibit a reduction as compared to low grade tumors, suggesting a different influence of SIRT7 in tumor progression at different stages of this malignancy." (PMID 38383727, 2024). "Moreover, a previous study shows that overexpressing SIRT7 promotes the proliferation and invasion of tumor tissues through its-related signaling pathway, which is similar with our results." (PMID 38360598, 2024). "Resveratrol promotes SIRT7 deacetylation, which inhibits tumor cell invasion and survival." (PMID 39479446, 2024). "This includes downregulation of prominent tumor suppressor microRNAs targeting SIRT7, upregulation of circular RNAs sponging these molecules or deregulation of specific factors controlling SIRT7 protein stability." (PMID 38383727, 2024). "In tumors, SIRT7 exhibits pro- or anti-tumor functions in a context-dependent manner." (PMID 39519130, 2024). "Similarly, SIRT7 has always been shown to have inhibitory effects on proliferation and migration, and promotive effects on apoptosis in tumor cells." (PMID 39020302, 2024). "Although most studies have shown that high SIRT7 expression is positively correlated with tumor migration, invasion, and proliferation, the effect of SIRT7 on chemotherapy resistance is still unknown." (PMID 38894712, 2024). "To date, these findings suggest that SIRT7 is a potential therapeutic target for tumor therapy." (PMID 38894712, 2024). "Notably, SIRT5 oscillates between oncogenic and tumor-suppressive roles by regulating key metabolic enzymes; whereas, SIRT7 drives PCa proliferation and metabolic stress adaptation through its chromatin and nucleolar regulatory functions." (PMID 39796040, 2024). "SIRT7 depends on CHD1L to exert its tumor-promoting functions." (PMID 37691108, 2023). "Apart from the protective effect on tumor cell survival, tumorous SIRT7 could also suppress CD8+T cell-dependent anti-tumor immunity to facilitate immune evasion." (PMID 36918544, 2023). "However, in SIRT7-knockdown plus LAP2α-overexpression group, we observed a slightly greater increase in the tumor volume and weight than in the control group." (PMID 37056924, 2023). "Furthermore, tumors with SIRT7 deficiency showed reduced Ki67 expression and up-regulated cleaved caspase-3 level, heralded that SIRT7 enabled tumor growth by inhibiting cell apoptosis." (PMID 36918544, 2023). "The roles of SIRT7 in tumor development remain to be controversial." (PMID 37691108, 2023). "As quantified by the tumor growth curve and tumor weight, we confirmed that SIRT7 could accelerate in vivo tumor proliferation, which could be repressed by CHD1L-KD." (PMID 37691108, 2023). "Targeting SIRT7 might potentiate the anti-tumor capacity of cytotoxic CD8+T cells and increase the efficacy of anti-PD-1 immunotherapy." (PMID 36918544, 2023). "In addition, PD-L1 antibody co-treatment prominently abrogated the protective effect of SIRT7 overexpression on tumor cells pre-treated with TG in response to T cell-mediated killing function." (PMID 36918544, 2023).
tumor (continued). "Interestingly, in these tumor datasets, the incidence of SIRT7 gene alterations was low, with SIRT7 gene amplification being the most prevalent form of mutation." (PMID 38234684, 2023). "We also examined the role of SIRT7 in anti-tumor immunity under stress in vivo." (PMID 36918544, 2023). "Previous studies have shown that SIRT7 plays a dual role in tumor development." (PMID 37056924, 2023). "Furthermore, the relationship between SIRT7 expression and tumor characteristics in patients with CSCC was analyzed through the clinical data of 305 CSCC patients in the TCGA database." (PMID 37957720, 2023). "Based on this, the knockdown of SIRT7 could prominently increase the treatment efficacy of anti-PD-1 antibody by potentiating CD8+T cell-dependent anti-tumor immunity." (PMID 36918544, 2023). "Moreover, SIRT7 up-regulation eradicated anti-tumor immunity by promoting PD-L1 expression via the IRE1α-XBP1 axis." (PMID 36918544, 2023). "In addition, the invigoration of tumor-infiltrating CD8+T cells by targeting tumorous SIRT7 and sustained PD-L1 expression can provide the cellular and molecular basis to potentiate the efficacy of anti-PD-1 immunotherapy." (PMID 36918544, 2023). "It should be noted that IFN-γ derived from infiltrated CD8+T cells is a cardinal trigger of PD-L1 expression in tumor cell, which prompted us to examine whether SIRT7 affects IFN-γ-driven PD-L1 up-regulation." (PMID 36918544, 2023). "Moreover, the tumor images revealed that SIRT7 silencing decreased mouse tumor size and weight compared with the shNC group." (PMID 37957720, 2023). "Inhibition of SIRT7 using small interfering RNAs inhibits tumor resistance to radiation." (PMID 35136826, 2022). "Thus, SIRT7 O-GlcNAcylation at S136 increases the SIRT7 recruitment at the promoters of tumour suppressor genes to inhibit their expression, leading to tumour progression." (PMID 35422493, 2022). "Because SIRT7 has oncogenic properties, we investigated whether the extension of lifespan in male Sirt7 KO mice was due to the reduced incidence of neoplasms." (PMID 36429037, 2022). "In addition, SIRT7 regulates rRNA and tRNA synthesis, which ultimately leads to an enhancement of ribosome biogenesis necessary for tumour cell growth and proliferation." (PMID 35422493, 2022). "Here, we find SIRT7 decline markedly attenuates the anti-tumor effect of IF." (PMID 34433808, 2021). "This suggests that Sirt7 downregulation favors tumor progression." (PMID 34433808, 2021). "To that end, we generated tumor xenografts by implanting 4T1 cells that were stably transfected with Sirt7 shRNA (KD7) or scramble shRNA (Scram) in female Balb/c mice subjected to IF for 48 h starting on day 16 and day 22, respectively; otherwise, all animals were provided with food ad libitum." (PMID 34433808, 2021). "Therefore, SIRT7 seems to be dynamically self-regulated in tumor progression, which hinders the understanding of its role in a specific case." (PMID 33498521, 2021). "Sirt7 KD significantly promoted tumor growth and while SIRT7-WT and SIRT7-2E apparently counteracted this effect, SIRT7-2A did not, indicating that the hyperphosphorylated form, SIRT7-2E, mediated the most effective inhibition." (PMID 34433808, 2021). "We next investigated the role of SIRT7 in fasting-induced tumor growth retardation." (PMID 34433808, 2021). "SIRT7 was significantly up-regulated in 9 of 10 tumor types and down-regulated in COAD." (PMID 33681201, 2021).
tumor (continued). "The importance of SIRT7 in DNA damage repair suggests that this enzyme might function as a tumour suppressor." (PMID 34129782, 2021). "Therefore, the relationship between SIRT7 transcription level and tumor prognosis warranted exploration." (PMID 32528869, 2020). "All examples show that SIRT7 mediates ambivalent effects in tumor biology." (PMID 32214204, 2020). "Additionally, SIRT7 upregulates rRNA synthesis, to meet the increased demand for ribosomes in rapidly growing tumor cells." (PMID 33274232, 2020). "SIRT7 could be a tumor suppressor and a biomarker to evaluate the treatment effects in myeloid stem-cell disorders." (PMID 32214204, 2020). "Additionally, SIRT7 participates in many molecular processes, including rRNA and tRNA synthesis, which enhance ribosome biogenesis that is responsible for tumor cell proliferation." (PMID 33274232, 2020). "However, SIRT7 was significantly reduced in cultured chemoresistant OC cells and was considered a tumor suppressor based on its inhibition of the activity of HIF-1 and HIF-2 transcription factors." (PMID 31572453, 2019). "It has been revealed that MYB binding protein 1, (Mybbp1), a component of the B-WICH chromatin remodeling complex, is capable of inhibiting the deacetylation of H3K18Ac by SIRT7, and it therefore may function as a tumor suppressor." (PMID 31121824, 2019). "Similar to other sirtuins, SIRT7 also functions as a tumor suppressor for cell growth." (PMID 31817470, 2019). "Although additional future studies are needed to identify the detailed mechanism, our results indicated that SIRT7 suppressed the EMT in OSCC metastasis by promoting SMAD4 deacetylation, which constitutes an important insight into the role of SIRT7 in tumor metastasis." (PMID 30001742, 2018). "We have shown that SIRT7, a newly discovered and pivotal regulator of lifespan and aging, acted as a tumor metastasis-suppressing gene in OSCC, as shown by its downregulation promoting OSCC cell line invasion and migration (whereas its overexpression suppressed metastasis)." (PMID 30001742, 2018). "This study emphasized the novel and necessary role of SIRT7 in tumor metastasis." (PMID 30001742, 2018). "The induced expression of Sirt7 was observed in primary tumors and isolated tumor cells." (PMID 28827661, 2017). "Thus, it is possible that SIRT7 itself is dynamically regulated during tumor development, and at early stage, high SIRT7 promotes oncogenic transformation and tumor growth, but later on, it rather inhibits dissemination, migration, and invasion." (PMID 28827661, 2017). "The function of SIRT7 in tumor development is seemingly controversial in the literature." (PMID 28827661, 2017). "Furthermore, SIRT7 inactivation suppresses migration of cancer cells and tumor metastasis formation in a mouse model." (PMID 26798421, 2016). "Recent studies reported that SIRT7 has tumor promoting activities." (PMID 27916001, 2016). "Similarly, high SIRT7 expression correlated withadvanced tumor stage and decreased overall and disease-free patient survival in coloncarcinoma cells." (PMID 25923013, 2015). "Furthermore, patients with low levels of tumour SIRT7 nuclear expression demonstrated a decrease in disease-specific time (p = 0.026, mean disease-specific time 26.9 vs 43.1 months)." (PMID 26121130, 2015). "Further studies are needed to test whether SIRT7 might function as a tumor suppressor in some contexts." (PMID 25085992, 2014). "Specifically, molecular changes in SIRT3 and SIRT7 expression may contribute to tumour development and disease progression." (PMID 17003781, 2006). "However, the mechanistic roles and clinical implications of SIRT7 expression in tumor development and progression remain unclear." (PMID 40165597, 2025).